MMP2 (matrix metallopeptidase 2)
Diseases named in the same sentence as MMP2 in open-access papers (continued):
Sharing a sentence is not in itself a finding about the gene and the disease.
cancer (continued). "We then analyzed by RT–PCR the mRNA level of EGFR and of a small number of proteins involved in its activation and/or having prognostic value in cancer diseases: MMP-2 and -9; uPA; G Protein Coupled Receptor 1 (GPER1); Estrogen Related Receptor alpha (ERR-alpha); SRC; LDH-A and -B; HBEGF." (PMID 39329717, 2024). "The NF-κB pathway is involved in cancer metastasis via regulation of metalloproteinases MMP-2/9, which plays a key role in HCC invasion and metastasis, and consequently reduces MMP-2/9 in HepG2 cells under high glucose (HG) conditions; these cells are used as an in vitro model of HCC." (PMID 39057397, 2024). "Furthermore, the transcriptional downregulation of Mortalin was connected to a reduction in N-cadherin, fibronectin, MMP3, MMP7, MMP9, MMP2, vimentin, and hnRNP-K (key proteins involved in the cell migration and metastatic characteristics of cancer cells." (PMID 39456564, 2024). "Thus, the decreased expression of MMP-2 and -9 due to the downregulation of B7-H6 inhibits cancer cell death, metastasis, and invasion." (PMID 39408655, 2024). "At present, regarding the roles of molecular mechanism of SUZ12 in promoting cancer, previous studies displayed that it may silence p2111 and p2712 and upregulate cyclin D16 and MMP2/921 expression." (PMID 39400513, 2024). "Additionally, in cancer, MMP-2 is involved in promoting invasion and metastasis by facilitating the vascular endothelial growth factor (VEGF), insulin-like growth factor (IGF), and TGF-β dependent pathways." (PMID 39769454, 2024). "MMPs, particularly MMP-9 and MMP-2, are instrumental in cancer-related processes." (PMID 38693104, 2024). "Remarkably, these nanoparticles were found to impede the invasive and metastatic potential of cancer cells by modulating the expression levels of MMP-2, a key enzyme involved in the degradation of extracellular matrix components and a facilitator of cancer cell dissemination." (PMID 39839762, 2024). "Similarly, other polyphenolic compounds, such as curcumin, demonstrate broad-spectrum anti-cancer properties, including inhibition of MMP-2 and MMP-9." (PMID 39858430, 2024). "Also, MMP-2’s ability to degrade the ECM components enhances cancer cells’ migration through tissues." (PMID 37513440, 2023). "Furthermore, it has been shown that the attenuation of MMP-2 and 9 expressions can greatly reduce the invasiveness of cancer cells." (PMID 37700002, 2023). "The calculated specific activity of MMP-2 decreased with an increase in cancer grading." (PMID 36979935, 2023). "Also, it helps in the activation of the pro-MMP-2 protein, which is involved in cancer cell invasion." (PMID 37513440, 2023). "EGCG was also found to enhance the anti‐cancer effects of docetaxel and reduce MMP‐2 expression." (PMID 37697969, 2023). "lEVs from cancer cells are known to increase tissue remodeling and MMP2 expression." (PMID 36975533, 2023). "Matrix metalloproteinase 2 (MMP2) is another protein that is involved in progressive metastatic transformation of cancer cells, where its protease activity is involved in the digestion of basement membrane proteins, thereby facilitating cellular movement from the primary site." (PMID 36765584, 2023). "However, future studies are needed to identify new intracellular substrates and epigenetic functions of MT1-MMP and MMP-2 in cancer." (PMID 37298452, 2023). "Interestingly, in cancer cells, IL-8/17 induced enhanced activity of MMP-2/9, thus promoted cancer metastasis." (PMID 37766868, 2023). "Furthermore, the overexpression of MMPs, especially MMP-2 and -9, in the cancer microenvironment facilitates EMT via architectural changes in cells and tissues." (PMID 37495969, 2023). "Altogether, these results suggest that 5α-reductase inhibition may decrease cancer cell progression and migration via p21, Bcl-2, MMP2, MMP9, NF-κB, and GSK3β signaling pathways." (PMID 36800968, 2023).
cancer (continued). "Furthermore, Deng and colleagues showed that glucose-derived AGEs are elevated in the serum of CRC+ T2DM patients to activate the RAGE/ERK/SP1/matrix metallopeptidase-2 (MMP2) cascade reaction in cancer tissues to promote CRC invasion and metastasis." (PMID 36890832, 2023). "Additionally, the study demonstrates that sublethal concentrations of doxorubicin can promote cancer cell migration, but this effect can be countered by inactivating MMP‐2 and/or overexpressing CHK/MATK." (PMID 38064181, 2023). "Moreover, multiple studies emphasized the role of MMP-2 in metastasis in various cancers, including breast cancer." (PMID 37700002, 2023). "When MMP2 expression and activity in the endothelial cells were inhibited by knockdown with siRNA or with an inhibitor OA-HY, respectively, the transmigration of the cancer cells across an endothelial monolayer barrier on Matrigel was abrogated." (PMID 36677584, 2023). "Natural killer cells mediated cytotoxicity against cancer cell was reduced when exposed to MMP2." (PMID 36788565, 2023). "Additionally, the upregulation of MTDH increased the invasion of cancer cells by upregulation of matrix metalloprotease enzymes (MMPs), specifically MMP-2 and MMP-9." (PMID 36902125, 2023). "Moreover, EVs enriched in TNF1α, TGFβ, and IL-6, isolated from hypoxic human prostate (PC3) cancer cells, increased MMP-2, MMP-9, fibronectin, and collagen deposition and stimulated the recruitment of CD11b myeloid cells at the PMN." (PMID 37350937, 2023). "Combined with its excellent safety profile, these features suggest Neovastat may be an attractive candidate to target cancers in which MMP-2 is an important player." (PMID 38288108, 2023). "Similarly, the K672 and K799 sites of FBN1 were found to be hypersuccinylated in cancer cells, which prevents its binding to MMP2." (PMID 38144777, 2023). "In addition to directly secreting ECM-remodeling factors, cancer cells are able to produce exosomes loaded with lnc-MMP2-2 RNA, which promotes BBB disruption in vivo by modulating human brain microvascular endothelial cells." (PMID 37728789, 2023). "MMP-2-mediated degradation of Collagen I may be responsible for the decrease in micromechanical properties of cancer tissues." (PMID 37901315, 2023). "δ-tocotrienol has been reported to inhibit cancer cell invasion by downregulating MMP-2 and MMP-9." (PMID 38069361, 2023). "Furthermore, cancer cells treated with EA demonstrated a notable reduction in the secretion of matrix metalloproteinase (MMP)-2 and MMP-9." (PMID 38002335, 2023). "The content of MMP-9 is enhanced in comparison with MMP-2, particularly in HG cancer tissue." (PMID 36979935, 2023). "In 2017, Ji’s group reported a pH-responsive AuNP for targeted delivery of ALA to kill A549 cancer cells, and they later reported a pH and matrix metalloproteinase-2 (MMP-2) dual-responsive ALA prodrug nanoparticle for photodynamic killing of SCC-7 cancer cells." (PMID 36923350, 2023). "Furthermore, MMP2 expression was positively correlated with CAFs infiltration in almost all cancers." (PMID 36788565, 2023). "It has been suggested that D mannuronic acid, via inhibiting MMP-2 and -9, could be a potential anti-cancer agent." (PMID 37062547, 2023). "Notably, the identification of some Mmps (Mmp1, Mmp2, Mmp7 and Mmp9) has been reported as Myb-regulated genes in cancer cells." (PMID 37701782, 2023). "The study reveals that MMP‐2 has a dual role in cancer progression." (PMID 38064181, 2023). "However, chlorogenic acids have been found to inhibit cell migration and MMP-2 secretion of human glioma cells, highlighting their anti-cancer effects." (PMID 36903626, 2023). "MMP-2 and MMP-9 gene polymorphisms may affect their biological function, and thus their role in cancer development and progression." (PMID 37445754, 2023).
cancer (continued). "Our results indicated that cancer progression was potentiated by testosterone treatment and attenuated by 5α-reductase inhibition, leading to alterations in expression of cancer protein markers, including Bcl-2, MMP2, and MMP9." (PMID 36800968, 2023). "Moreover, ICAM1 and MMP2 presented higher expressions of COAD cancer tissues than in normal tissues." (PMID 37575276, 2023). "These two short peptide sequencesare well-known substrates of matrix metalloproteinase-2 (MMP-2) andcathepsin B, respectively, both of which are overexpressed in a widerange of cancer cells either extracellularly (for MMP-2) or intracellularly(for cathepsin B)." (PMID 36961946, 2023). "IL-17A mediates cancer cell invasiveness and metastasis via MMP-2, MMP-9, and MMP-13." (PMID 36993955, 2023). "Snail and MMP-2 are important markers in the process of cancer invasion." (PMID 37563232, 2023). "Chlorotoxin (CTX) is a promising 36-amino acid peptide isolated from the venom of the deathstalker scorpion, Leiurus quinquestriatus, demonstrating high selectivity and binding affinity to a broad-spectrum of cancers, especially GB and NB through specific molecular targets, including MMP-2." (PMID 37444498, 2023). "However, the presence of adipocytes from normal, overweight, or obese individuals alone increased the activity of MMP-2 in cancer cells (p < 0.0001)." (PMID 37686623, 2023). "Furthermore, in almost all cancers, MMP2 expression was positively correlated with CAFs infiltration." (PMID 36788565, 2023). "Additionally, western blot analysis revealed a downregulation of MMP-7 and MMP-2 protein expression after elaiophylin treatment, supporting the idea of its potential role in inhibiting the enzymatic activity involved in cancer cell migration and invasion." (PMID 37894684, 2023). "The principal MMPs involved in cancer are MMP-2, MMP-9, and, most notably, MMP-14." (PMID 36766694, 2023). "Thus, we conclude that preparations of hAM influence the invasion of T24 cancer cells by regulating MMP-2 expression and activity." (PMID 37932474, 2023). "Furthermore, we found that most MMPs, including Mmp2, Mmp3, and Mmp9, secreted by cancer cells can degrade ECM to promote cell invasion and migration, were up-regulated in hybrid cells." (PMID 37138326, 2023). "We conclude that a deeper understanding of the role of intracellular/nuclear MMP‐2 in cell migration may pave the way for new strategies to effectively target cancer migration and metastasis." (PMID 38064181, 2023). "MMP-2 and MMP-9 are reported to be associated with cancer cell invasion and metastasis." (PMID 36333531, 2022). "Matrix metalloprotease-2 (MMP-2) plays a pivotal role in cancer invasion and metastasis." (PMID 35641480, 2022). "Given the role of SP1 in responding to DNA damage — which would be present in both UVB-irradiated cells and cancer — we hypothesized that SP1 might directly mediate the induction of Mmp2 and Mmp11 mRNA by UVB." (PMID 35316219, 2022). "Exosomes from cancer stem cells could enhance the proliferative, migratory, and/or invasive abilities of fibroblasts, accompanied by the upregulated expression of MMP-2 and MMP-9." (PMID 36230852, 2022). "Furthermore, we adopted gain- and loss-of-function experiments, which demonstrated that miR-331-3p promotes the proliferation, migration, and invasion of PC cells, and also augments the expression of cancer cell metastasis markers, MMP-2 and MMP-9." (PMID 35510828, 2022). "MMP-2 is released by cancer cells and can specifically degrade collagen type IV." (PMID 36605288, 2022). "Additionally, MMP1 and MMP2 can enhance cellular growth and migration in cancer and wound-healing models." (PMID 35328555, 2022). "In consequence, inhibiting the expression and/or activity of MMP2 and 9 could represent an essential role in the inhibition of cancer metastasis." (PMID 35956938, 2022).
cancer (continued). "The MMP2 SNPs have been studied fairly extensively in the context of susceptibility to various cancers and non-malignant pathologies, but the results were inconclusive." (PMID 35406617, 2022). "MMP-2 localizes to specific intracellular compartments, including the cytosol, mitochondria, and nucleus, as first discovered to function inside cardiomyocytes and later inside other cell types, including cancer cells." (PMID 36076910, 2022). "We suggest that targeting nuclear MT1-MMP or MMP-2 to reduce or halt cell proliferation and migration may lead to the development of new therapies for cancer and other diseases." (PMID 36076910, 2022). "Interestingly, concentrations of MMP-9 were higher than MMP-2 levels (p < 0.0001) when both gelatinases were compared in cancer groups." (PMID 36213817, 2022). "ESCO2 has the ability to knock down MMP2, thus inhibiting migration of cancer cells." (PMID 35409426, 2022). "Additionally, we observed that TTYH1 effectively regulated the protein expression levels of MMP-2/9 and N-cadherin, which are involved in the migration and invasion of cancer cells." (PMID 35455021, 2022). "Bands corresponding to the MMP-2 active form were also identified in control and cancer patients." (PMID 36213817, 2022). "Additionally, MMP overexpression contributes to cancer cell invasion and metastasis, and IL‐8/STAT3 signaling in HNSCC can also upregulate the expression of MMP‐2 and ‐9 and play a key role in cancer invasion and metastasis." (PMID 35356799, 2022). "Cancer cell invasion and migration into adjacent tissues are mediated by MMP-2 and MMP-9." (PMID 35458783, 2022). "However, MMP members that have a major role in cancer cell migration and invasion include MMP-2 and MMP-9." (PMID 36605288, 2022). "Additionally, TP73 antisense RNA 1 (TP73-AS1) promotesovarian cancer cell proliferation and metastasis via modulation of matrixmetallopeptidase 2 (MMP-2) and matrix metallopeptidase 9 (MMP-9)." (PMID 35129574, 2022). "Due to the abundant evidence connecting N-cadherin and MMP2 with the invasion and metastasis of cancer, the effect of anlotinib identified in the present study indicates that progressive disease can be reduced by resistance to single-targeted anti-angiogenic drugs, as we have recently reported." (PMID 35664796, 2022). "We believe that such a technology may find future use in multiple diseases where MMP2/MMP9 gelatinases are overexpressed and play a pathogenic role (including cancer)." (PMID 35401813, 2022). "Although this is the first study to suggest that MK2 may directly regulate expression of some MMPs, one group demonstrated that MK2 inhibition attenuated MMP2-dependent cancer cell migration." (PMID 36558958, 2022). "Unlike these studies, exposure to morphine of the human cancer breast line MCF-7, resulted in inhibition of the expression of matrix metalloproteinases (MMP)-2 and -9 that are involved in the degradation of extracellular matrix, thus initiating the dissemination of invasive cancer cells." (PMID 35565382, 2022). "Previous studies have demonstrated the function of miR-34c-5p and MMP2 in cancer development." (PMID 35342412, 2022). "MMP2 is a member of the zinc-dependent metalloproteinase gene family that can degrade most components of the extracellular matrix and basement membrane, thus playing an important role in modulating cancer invasion and metastasis." (PMID 35723188, 2022). "It has been reported that IL-32 could promote the metastasis of cancer cells by up-regulation the expression of MMP2 and MMP9." (PMID 35428295, 2022). "Furthermore, we noticed a significant correlation of POSTN expression in cancer cells with MMP-2 expression levels in NSCLC." (PMID 35163164, 2022). "ID2 has been shown to mediate the expression of MMP2 in cancer cells." (PMID 35705978, 2022). "In addition, we demonstrated that CNTF downregulated MMP-2 expression which is the main MMP involved in cell cancer invasiveness." (PMID 36497399, 2022).
cancer (continued). "Clinical diagnosis and therapeutic evaluation of cancers are related to the MMP-2 activity in vivo." (PMID 36451698, 2022). "Carvacrol decreased cancer cells proliferation and apoptosis via decreasing matrix metalloprotease (MMP‐2, MMP‐9) expressions while downregulating the Bcl‐2 expression and inducing phosphorylation of extracellular regulated protein kinase and protein kinase B(p‐Akt) at the molecular level." (PMID 36348778, 2022). "Apart from the MMP‐2 and HAase, legumain that could hydrolyze asparagine in proteins and small molecule substrates was also overexpressed in a lot of cancers such as gastric cancer, ovarian cancer, and colorectal cancer." (PMID 34796689, 2022). "On the contrary, CP-25 and 5-Fu can significantly inhibit the expression and activity of MMP-2/-9, which implies that CP-25 and 5-Fu may through regulating MMP-2/-9 to against the metastatic effect of cancer cells." (PMID 35154466, 2022). "MMP-2, specifically, can cleave the adhesive contacts and the cellular networks that are important for adherence of cells to the basement membrane, thereby enabling the migration of cancer cells." (PMID 34638658, 2021). "Imine derivatives of hybrid chalcone analogues (13a, 13b, 13c, and 13d) containing anthraquinone scaffold exhibited significant anti-tubulogenic and anti-angiogenic effect against HeLa, LS174, and A549 cancer cells by inhibiting matrix metalloproteinase-2 (MMP-2) secretion." (PMID 34502529, 2021). "Additionally, to metastasize to other organs, cancer cells invade the extracellular matrix by increasing MMP-2 and MMP-9 activity." (PMID 33806109, 2021). "AP-1 transcriptional activity is critical for MMP-2-mediated cancer migratory activities." (PMID 34445345, 2021). "To further study this hypothesis, we analyzed the expression of MMP2, which is up-regulated by both estrogen receptors alpha and beta and promotes the invasion of multiple types of cancer." (PMID 34684173, 2021). "We also observed an increased expression of some metalloproteinases such as MMP14 and MMP2, which are known mediators of cancer invasion and a remarkable decrease of two metalloproteinases, MMP11 and MMP12, which are known to have a protective role against tumors." (PMID 34680461, 2021). "Previous studies demonstrated that MMP2/9 are important prognostic factors for various cancers." (PMID 33568081, 2021). "This study examined the effect of ATD on TGF-β1-induced expression of cancer cell progression associated proteins, and the results showed TGF-β1 promoted the expression of integrin α3, N-cadherin, vimentin, and MMP2, while TGF-β1 cotreated with ATD inhibited such expression." (PMID 34572296, 2021). "Moreover, the C-X-C motif chemokine receptor 7 signaling in cancer cells upregulates the expression and release of MMP2 and MMP9 into the extracellular matrix." (PMID 34588926, 2021). "Cancer cells were shown to express matrix metalloproteinase 2 (MMP2)." (PMID 34067049, 2021). "Recently, a functionalized liposomal nanocarrier containing a mAb with a MMP2 cleavable peptide that recognizes the cancer cells has been designed, which releases the encapsulated therapeutic compound that has cytotoxic effects for cancer cells." (PMID 33809973, 2021). "In platelet-treated cancer cells, mesenchymal markers Snail family transcriptional repressor-1, vimentin, N-cadherin, fibronectin and matrix metalloproteinase 2 (MMP-2) are frequently upregulated, while the epithelial markers (E-cadherin, claudin-1) are downregulated." (PMID 34322381, 2021). "The involvement of MMP-2 in cancer has been studied in different malignancies." (PMID 35201460, 2021). "At the same time, specific MMP-2/-9 inhibitors could be promising radiosensitizers in cancer therapy." (PMID 34055644, 2021). "MMP-2 is a widely known influencer of vascularization during cancer development." (PMID 35145899, 2021).